IL2 (interleukin 2)
Diseases named in the same sentence as IL2 in open-access papers (continued):
Sharing a sentence is not in itself a finding about the gene and the disease.
acute GVHD (22 papers, 2006 to 2025). "Specifically, IL-2, IL-9 and their analogs promote the expansion of Tregs, thereby suppressing acute GVHD." (PMID 40943537, 2025). "This means that our study did not have the opportunity to widen its considerations on more cytokines such as IFN-γ, G-CSF, GM-CSF, IL-2, IL-3, IL-5, and IL-13, which all have a known role in acute GVHD." (PMID 39728035, 2024). "Although the Th1 cell‐associated cytokines IFN‐γ, IL‐2 and TNF‐α have been implicated in the pathophysiology of acute GVHD, some studies have reported the opposite effects." (PMID 35844683, 2021). "Taken together, inhibition of T cell proliferation via IL-2 blockade can be achieved by calcineurin inhibitor such as CsA, and this would be advantageous for prevention of acute GVHD during early post-transplant period." (PMID 27494893, 2016). "Based on the cytokine profile, the Th1 cytokines (IFN-γ, IL-2, and TNF-α) have been implicated in the pathophysiology of acute GVHD." (PMID 25541735, 2014). "The recipient mice develop acute GVHD within the first week after transplantation, and the maximum serum levels of IFNγ, TNFα and IL2 are reached at day 5 post transplantation." (PMID 23593203, 2013). "Together these results confirm the critical role of IL-2 in initiating acute GVHD and demonstrate that TNF, an IL-2 dependent cytokine in this context, is necessary and sufficient to drive CD8 SLEC maturation in the absence of significant levels of inducers of IFNα or IL-12." (PMID 38915570, 2024). "Further, increases in several cytokines could trigger kidney injury in acute GVHD; when acute GVHD occurred, interleukin (IL)-2, IL-6, or tumor necrosis factor-α was upregulated in the kidney." (PMID 30842899, 2019). "Furthermore, IFN-γ and IL-2 were shown to induce acute GVHD grades II-IV." (PMID 39170616, 2024). "As acute GVHD can be inhibited by the addition of neutralizing anti-IL-2 monoclonal antibodies (mAbs) and is not induced by perforin-deficient donor T cells, acute GVHD is associated with increased Th1-mediated immune responses and with perforin expression on donor T cells." (PMID 16859527, 2006). "In B6→F1 acute GVHD, B6 donor CD4 T cells produce a strong initial IL-2 response, which in turn promotes a Th1-dominant response consisting of robust TNF and IFNγ production." (PMID 38915570, 2024). "Inflammatory mediators, such as interleukin-33, interleukin-1β, type 1 helper T cell cytokines (interferon-γ, interleukin-2, TNF), and reactive oxygen species, were also correlated with acute GVHD." (PMID 35905125, 2022). "Acute GVHD has been proposed to be mediated by Th1-type cells and their inflammatory cytokines including IFN-γ, IL-2 and TNF-α." (PMID 23593203, 2013). "We found higher levels of IFN-γ, IL-2, IL-5, IL-13, GM-CSF, and G-CSF, but lower VEGF in hospital-treated patients, which may contribute to acute GVHD grades II-IV." (PMID 39170616, 2024). "Prevention of acute GVHD by SD-36 treatment of WT T cells was associated with lower serum concentrations of IFN-γ, TNF-α, and IL-6, but not IL-2, and was confirmed by histopathology." (PMID 37526084, 2023). "To determine whether GMSCs could suppress acute GVHD through controlling cytokine production by staining with IFN-γ, IL-17, IL-4, TNF-α, IL-2, and IL-10, we detected the production of cytokines after injecting 15 days." (PMID 30622237, 2019). "While we do not know the exact mechanism of why CSA and IL-2 cancel out each other's beneficial effects in the treatment of acute GVHD, we propose that this combination should be avoided in this disease setting." (PMID 24658577, 2014). "Thus, many factors contribute to why a calcineurin inhibitor would not synergize with IL-2 to protect against acute GVHD." (PMID 24658577, 2014).
acute GVHD (continued). "Unlike the syngeneic setting, CsA and IL-2 does not suppress allogeneic immune responses, indicating that IL-2 treatment against acute GVHD would not be recommended in the clinical setting because almost all recipients are treated with a calcineurin inhibitor for GVHD prophylaxis." (PMID 24658577, 2014). "Interestingly, the upregulation of CD25 on these NK cells may have enabled them to competitively sequester IL-2, thereby influencing Treg function without leading to an exacerbation of acute GVHD severity." (PMID 40943537, 2025).
Alzheimer disease (21 papers, 2013 to 2025). A progressive, neurodegenerative disease characterized by loss of function and death of nerve cells in several areas of the brain leading to loss of cognitive function such as memory and language. "Pathway enrichment analysis based on Enrichr showed that Trem2-KO responsive genes were enriched with genes associated with interleukin-2 signaling pathway, lysosome, and Alzheimer's disease." (PMID 37246643, 2023). "We observed some evidence for a detrimental effect of greater levels of CTACK (CCL27), MIP-1b (CCL4), Eotaxin, GROa (CXCL1), MIG (CXCL9), IL-8 and IL-2 on the risk of Alzheimer’s disease." (PMID 35580794, 2022). "Regarding these cytokines, there is a reported that association between polymorphisms in IL-16 and IL-2 genes and the risk of late-onset Alzheimer’s disease." (PMID 34302237, 2021). "IL-2 deficiency is associated with impaired learning in mice, similar to Alzheimer’s disease, while knockout of IL-2 leads to impaired spatial learning and memory and morphological changes in the hippocampus." (PMID 33921854, 2021). "Brain-derived interleukin-2 (IL-2) has been implicated in diseases processes that arise during CNS development (e.g., autism) to neurodegenerative alterations involving neuroinflammation (e.g., Alzheimer’s disease)." (PMID 24563821, 2013). "Research has implicated both peripheral immune and brain-derived interleukin-2 (IL-2) in neurologic disease processes that arise during CNS development (e.g., autism) to neurodegenerative alterations involving neuroinflammation (e.g., Alzheimer’s disease)." (PMID 24563821, 2013). "For IL-2, a detrimental causal effect on Alzheimer’s disease risk was observed (Wald Ratio: OR = 1.03 95% CI: 1.00 to 1.06, p = 0.04), although the effect estimate was much smaller in magnitude compared to analyses including only diagnosed cased of Alzheimer’s disease." (PMID 35580794, 2022). "Several studies have reported that increased levels of IL-2 play a prominent role in exacerbating neurodegenerative processes in various neurological disorders such as Alzheimer’s disease." (PMID 38107411, 2023). "IL-2 and GSK3B proteins are T and natural killer (NK) cell regulators and have previously been associated with other neurodegenerative diseases such as Alzheimer’s disease, Parkinson’s disease and multiple system atrophy." (PMID 31123295, 2019). "Multiple brain cytokines were elevated in Alzheimer’s disease and vascular dementia: IL-15 and IL-17A were maximally elevated in end-stage Alzheimer’s disease (Braak tangle stage V–VI) whereas IL-2, IL-5, IL12p40 and IL-16 were highest in intermediate Braak tangle stage III–IV disease." (PMID 33723589, 2021). "When we analyzed the production of cytokines among the elderly with or without Alzheimer’s disease, we observed that the elderly with Alzheimer’s have increased IL-2 production." (PMID 40869831, 2025). "In controls, cortical perfusion declined with increasing IFN-γ, IL-2, IL-4, IL-6, IL-10, IL-12p70, IL-13 and tumour necrosis factor-α (TNF-α) but these relationships were lost with progression of Alzheimer’s disease, and with infection (even in Braak stage 0–II brains)." (PMID 33723589, 2021). "In Alzheimer’s disease, a systematic review of peripheral inflammatory markers showed IL-2 but not IL-8 was consistently raised." (PMID 30403785, 2018). "For many cytokines, (IL-5, IL-2, IL-12p40 and IL-16), however, the level was highest in BSIII–IV disease, suggesting perhaps that the deleterious effects of systemic infection on the brain are likely to be maximal at an early to intermediate stage of Alzheimer’s disease." (PMID 33723589, 2021).
B cell lymphoma (21 papers, 2004 to 2026). "The aim of the current work was to study the possible role of IL-2-330T/G (rs2069762) and IL-10-1082A/G (rs1800896) single-nucleotide polymorphisms (SNPs) as genetic risk factors for B-cell NHL (B-NHL) in a group of Egyptian patients." (PMID 28713071, 2018). "To explore the possible association between IL-2-330T/G and IL-10-1082A/G single-nucleotide polymorphisms and the susceptibility to B-cell NHL (B-NHL) in Egyptians, we conducted a case-control study." (PMID 28713071, 2018). "In B cell lymphoma, promising data were obtained in both preclinical models and in the clinic with administration of IL-2 plus rituximab (anti-CD20) combination." (PMID 39204319, 2024). "In this context, we previously demonstrated using A20luc/YFP cells (murine B cell lymphoma) that transplanting donor TL1A-Ig + IL-2 spleen cells (containing ~4 × 105 Tregs) GVHD was significantly reduced and GVL was preserved." (PMID 30733722, 2018). "We also explored the underlying mechanism by which TGF-β mediates the regulation of T cell differentiation in B-cell NHL and found that IL-2 signaling was critically involved." (PMID 23555036, 2013). "Denileukin diftitox is a fusion protein combining the cytotoxic portion of the diphtheria toxin and the receptor-binding domain of the interleukin-2 (IL-2) molecule, thereby targeting cells expressing the IL-2 receptor, including both T-cell and B-cell lymphomas." (PMID 26240767, 2015). "This was the first study demonstrating activation of Vγ9Vδ2 T cells in patients with B-cell lymphomas by Pamidronate and low-dose IL-2 was well tolerated and induced a clinical response; moreover, the immunologic and clinical outcome could be nicely predicted by Vγ9Vδ2 T cell proliferation in vitro." (PMID 29163482, 2017). "The complex of sIL-2Rα and IL-2 promotes IL-2-dependent Tregs development and function, and inhibits CD8+ T-cells, supporting B-cell lymphoma growth." (PMID 32973297, 2020). "CONCLUSIONS: These findings described the detailed mechanism of action of L19IL2 against B cell lymphoma and revealed for the first time the dynamic responses of peritumoral CD8+ T cells to targeted IL2 stimulation, supporting the use of L19IL2 for patients with aggressive B cell lymphoma." (PMID 41776565, 2026). "In order to target IL-2 to tumor in a way of reducing its potential toxicity, Merck KGaA (Darmstadt, Germany) developed a novel fully humanized IL-2 fusion protein, EMD521873 or NHS-IL2LT (Selectikine), for the treatment of solid tumors and B-cell non-Hodgkin lymphoma." (PMID 23294527, 2013). "Additionally, CLBL-1 was stimulated with IL-2 and DSP30 as described for primary canine B-cell lymphomas and NHL to examine the stimulatory effect on cell proliferation." (PMID 22761949, 2012). "Combination treatment of recombinant IL-2 and IL-12 has been reported to be synergistic for inducing anti-tumor responses in solid tumors but the potential of IL-2/IL-12 gene modified B cell lymphoma cells has not been explored yet." (PMID 15485577, 2004). "Vδ2 T cells from patients with B-cell lymphoma and MM, expanded in vitro by culture with zoledronate and IL-2, displayed enhanced cytotoxic effects towards MM/B-cell lymphoma cell lines and autologous tumor cells, without cytotoxicity against normal cells in these patients." (PMID 37426670, 2023). "However, the significance of IL-2 and IL-12 immunogene therapy of hematopoietic neoplasms such as B cell lymphoma, has not been addressed yet." (PMID 15485577, 2004).
celiac disease (21 papers, 2008 to 2026). An autoimmune genetic disorder with an unknown pattern of inheritance that primarily affects the digestive tract. "This particular variant is considered a risk variant for T1D and celiac disease, and correlated with impaired IL-2 signalling in CD4+ T cells as measured by decreased phosphorylation of STAT5 (pSTAT5) but also reduced PTPN2 expression." (PMID 33193091, 2020). "A new whole blood assay measuring IL-2 (WBAIL-2) with potential to aid in the diagnosis of celiac disease has been described." (PMID 41374379, 2025). "The IL-2 assay demonstrated high accuracy for celiac disease diagnosis, even in patients consuming a strict gluten-free diet, with a sensitivity and specificity of 90% and 95%, respectively, for HLA-DQ2.5+ patients." (PMID 41374379, 2025). "In the following part, the roles of these critical genes in celiac disease will be described and discussed: IL2 the top hub-bottleneck node is a highly connected node that interacts with 113 nodes directly." (PMID 34466507, 2019). "This rise in interleukin-2 appears to be unique to those with celiac disease." (PMID 41158112, 2026). "NHL and celiac diseaseCD79B (NHL) and IL2 (Celiac Disease) the relationship between IL2’s function in T-cell activation in Celiac disease and CD79B’s role in B-cell receptor signaling in NHL suggests a possible link between lymphocyte dysregulation in both conditions." (PMID 40321894, 2025). "As regards coeliac disease diagnosis above 7 years of age in the case–control analysis, rs653178 (at SH2B3/ATXN2), rs13010713 (at ITGA4/UBE2E3), rs13151961 (at IL2/IL21), rs11712165 (at CD80) and rs10936599 (at MYNN) showed an association." (PMID 33446885, 2021). "IL-2 has been shown to have high sensitivity and specificity in distinguishing celiac disease patients from healthy controls, as well as non-celiac gluten sensitivity." (PMID 41374379, 2025). "Lastly, four of the nine TPOA associated SNPs (in SH2B3, CTLA4, BACH2 and UBASH3A) have also been associated with celiac disease (but not the SNPs in RASGRP1, STAT4, PTPN22, IL2 and FCRL3)." (PMID 21829393, 2011).
cutaneous T-cell lymphoma (21 papers, 2008 to 2024). "Intriguingly CARMIL2 can also work in a dominant mode, as a gain-of-function mutation (Q575E) has been linked to cutaneous T cell lymphoma, selectively upregulating the NF-κB pathway and causing activated T cells to significantly increase their IL-2 production." (PMID 29479355, 2018). "The strongest candidate drug of all in terms of degree of association is denileukin diftitox (an IL2 binding cytocidal agent) that is currently used in cutaneous T-cell lymphoma, although its action on IL2 is agonistsic/binding." (PMID 38862968, 2024). "Some fusion biopharmaceutical proteins are available in the market and represent a substantial part of the drug market, such as Ontak®(IL-2 and denileukin diftitox for cutaneous T-cell lymphoma) and Idelvion® (Factor IX and albumin for hemophilia B)." (PMID 36777254, 2023). "Ontak, an interleukin-2- diphtheria toxin fusion protein was FDA-approved for cutaneous T cell lymphoma but has since been discontinued due to production issues." (PMID 36650239, 2023). "Diphteria toxin-IL-2 fused proteins showed promising results in a phase III trials of cutaneous T cell lymphoma (CTCL) patients." (PMID 35529882, 2022). "The effects of 100 μM of 3′,5′-cGMP, cAMP, cCMP, and cUMP as well as of the corresponding membrane-permeant acetoxymethyl esters on anti-CD3-antibody (OKT3)-induced IL-2 production of HuT-78 cutaneous T cell lymphoma (Sézary lymphoma) cells were analyzed." (PMID 32313990, 2020). "DAB/IL2 is FDA-approved for the treatment of patients with persistent or recurrent cutaneous T cell lymphoma (CTCL) whose malignant cells express CD25." (PMID 18334033, 2008). "Preliminary Phase I data clarified that BNZ-1 was well tolerated and inhibited IL-2 and IL-15 activity, leading to clinical improvement in participants with cutaneous T-cell lymphoma (CTCL) by rejuvenating anti-lymphoma immunity and reducing inflammatory responses (NCT03239392)." (PMID 37483629, 2023). "The fact that interleukin-2 in denileukin diftitox (Ontak®) is an agonist ligand of the interleukin-2 receptor in the treatment of cutaneous T-cell lymphoma may support the potential therapeutic use of FL-DM1." (PMID 33691697, 2021). "Recombinant IL-2/diphtheria toxin fusion protein (rIL-2/DTx), a drug that is FDA-approved for the treatment of cutaneous T cell lymphoma, has been reported to deplete regulatory CD4+ T cells." (PMID 21909452, 2011). "IL-2 can be used as a single drug treatment for cancer therapies, or it can be combined with other chemotherapy; for example, IL-2 fused with Diphtheria toxin proteins showed promising results in phase III trials of cutaneous T cell lymphoma (CTCL) patients." (PMID 36679904, 2022). "Denileukin diftitox (rIL-2/diphtheria toxin [DTx]), a recombinant fusion protein composed of the membrane-translocating and cytotoxic domains of diphtheria toxin (Met1-Thr387)-His and human interleukin 2 (Ala1-Thr133), is FDA-approved for the treatment of cutaneous T cell lymphoma." (PMID 21909452, 2011).